BRCA2 (BRCA2 DNA repair associated)
Diseases named in the same sentence as BRCA2 in open-access papers (continued):
Sharing a sentence is not in itself a finding about the gene and the disease.
cancer (continued). "Here, using next-generation sequencing we comprehensively surveyed genomes to identify DSBs in primary cells of non-malignant carriers of BRCA1 and BRCA2 mutations (BRCAmut), categorized as high-risk patients, to characterize the effects of homologous recombination (HR) loss on cancer initiation." (PMID 41350536, 2025). "Finally, we sought to determine whether the combination of CldU and PARP inhibition induces DNA damage in BRCA2-mutant cancer cells." (PMID 41347092, 2025). "The seminal discovery of the ability of early PARP small molecule inhibitors, or PARP1 silencing, to selectively kill BRCA1- or BRCA2-deficient cells, kickstarted the development of clinically approved PARPi, which have shown significant efficacy as monotherapy in HRR-deficient cancers." (PMID 41459749, 2025). "The abundance and stoichiometry of splice-variant proteins may be another factor influencing the cancer phenotype in BRCA2-associated FA, which, so far, has not been investigated and would warrant further experimental interrogation." (PMID 40724944, 2025). "An example may be the use of poly (ADP-ribose) polymerase (PARP) inhibitors (PARPis), drugs with already proven effectiveness in humans, for treatment of patients with DNA damage repair-deficient cancers, mainly with Breast Cancer Associated 1 and 2 (BRCA1 and BRCA2) mutations." (PMID 40616061, 2025). "For example, reversion mutations or epigenetic alterations leading to the re‐expression of a BRCA1 or BRCA2 wild‐type protein or resulting in hypomorphic variants are common resistance mechanisms to PARPi, which is also the main mechanism for platinum resistance in BRCA1/2‐mutated cancer." (PMID 40980974, 2025). "Interestingly, PALB2 has a close interaction with BRCA1 and BRCA2, which could lead to malignant tumors." (PMID 40507905, 2025). "However, the concept gained traction in cancer therapy when researchers recognized that cancer cells, particularly those with certain gene mutations such as BRCA1 and BRCA2, could be selectively targeted using specific inhibitors." (PMID 40450009, 2025). "Strikingly, carboplatin did not improve pCR rates in BRCA1- or BRCA2-associated carcinomas." (PMID 40547808, 2025). "Another key distinction between BRCA1 and BRCA2 in terms of cell cycle protein expression involves type D cyclins (D1, D3), their associated CDK such as CDK4, and the CDKIs p16, p21, and p27, which showed a lower expression in BRCA1 compared to BRCA2 carcinomas." (PMID 40136510, 2025). "For the patients with single primary cancer, among 542 evaluable patients (those with both germline and somatic mutations which were in same or different genes), 25 patients (4.6%) had biallelic events, and the involved genes included ATM, BRCA1, BRCA2, BRIP1, and ERCC5." (PMID 37885353, 2024). "Furthermore, BCAC and Cancer Risks Estimates Related to Susceptibility Consortium (CARRIERS), suggested BRCA1, BRCA2, ATM, PALB2, and CHEK2 genes as highly penetrant; both consortiums pinpointed that 10% of BC patients have cancer susceptibility germline mutation." (PMID 38890714, 2024). "In Case 3, a CDK12 variant was detected in all cells of Regions A and B; whereas, four variants in ATRX, BRCA2, PIK3CA, and PPARG were detected specifically in Region A. All four variants displayed low VAFs (0.05–0.07), indicating a late molecular event present in a small subset of cancer cells." (PMID 39766052, 2024).
cancer (continued). "Of the 556 BRCA PV carriers identified in the 11,482 cancer patients, 331(59.5%) were the carriers for the three founder variants, including 24 (4.3%) carriers of BRCA1 c.2037delinsCC, 58 (10.4%) carriers of BRCA1 c.3331_3334del, and 249 (44.8%) carriers of BRCA2 c.156_157insAlu." (PMID 38671360, 2024). "Additionally, the identification of alkylated MGMT and MGMT inhibitors promoting the degradation of BRCA2 presents a promising strategy for targeting homologous recombination proficient cancers with MGMT inactivators in conjunction with DNA crosslinking agents." (PMID 38254819, 2024). "For example, the identification of BRCA1 and BRCA2 mutations in breast cancer, mutL homolog 1, mutS homolog 6, and mutS homolog 6 mutations in colon cancer, and the RB1 mutation in retinoblastoma is useful for understanding cancer progression in relation to different prognoses and treatments." (PMID 39767566, 2024). "Moreover, they showed that BRCA2 mutations should be considered an independent negative prognostic factor based on both the significantly shorter 5-year cancer-specific survival and metastasis-free survival among mutation carriers." (PMID 38534919, 2024). "Preclinical studies suggest that cancer cells with alterations in other homologous recombination (HR) repair pathway genes (e.g., ataxia telangiectasia mutated (ATM) and partner and localizer of BRCA2 (PALB2) may also be sensitive to PARP inhibition." (PMID 39085400, 2024). "Furthermore, carriers of harmful BRCA1 and BRCA2 variants typically manifest the onset of cancer at earlier ages compared to non-carriers." (PMID 38809921, 2024). "However, because elevated Tspan8/Thrsp expression was accompanied by an interferon response in our model, we next investigated whether BRCA2-mutant cancers displayed increased interferon response pathway expression." (PMID 37626143, 2023). "We did not identify any mutations which were directly homologous to the human BRCA1 and BRCA2 germline variants which have been confirmed to increase the risk of cancer in humans, however we did find variants which potentially could influence the function of the BRCA1 and BRCA2 proteins." (PMID 36635367, 2023). "As a result of nonsense mutations in BRCA1 and BRCA2, DSB repair cannot efficiently take place, and this results in continuous genome instability, high mutational load, chromosomal rearrangements, and overall defective genome maintenance, which results in cancer development." (PMID 38017453, 2023). "Similarly, survival was significantly worse if tumors were ER+ than ER-negative for BRCA2 carriers and non-significantly worse for young patients, whereas ER+ cancer was associated with good prognosis among older patients as expected." (PMID 38036573, 2023). "We therefore asked whether this phenomenon extended beyond FA and tested if somatic polygenic RAD51C + BRCA2 mutations in tumors of cancer patients without FA could similarly show functional synergism." (PMID 36906610, 2023).
cancer (continued). "Identifying germline mutations in BRCA1 and BRCA2 genes would benefit the carriers by taking risk-reducing interventions before they get a cancer, as well as providing valuable information on the therapeutic application of Poly (ADP-ribose) polymerase inhibitors after a cancer occurs." (PMID 38274092, 2023). "However, its incidence can be higher among males with either genetic disorders or germline mutations in cancer susceptibility genes (BRCA2, CHEK2, ATM and PALB2) regardless of family history." (PMID 37148499, 2023). "The rising interest in APE2 as a drug target for precision medicine in chemotherapy is largely due to the multiple reports of its SL with BRCA1- and BRCA2-deficient cell lines, suggesting that inhibiting APE2 may lead to the loss of viability in BRCA1/2-deficient cancer cells." (PMID 36755963, 2023). "Although germline variants in BRCA1, BRCA2 and other HR repair (HRR) pathway genes have been described in large sequencing studies of pediatric oncology patients, the relevance of these findings to pediatric cancer pathogenesis remains unclear." (PMID 36585449, 2023). "Although we did not found a significant association between ATM and PanC, based on this observation an effect of ATM on cancer germline predisposition not independent of BRCA2 might be supposed." (PMID 36717774, 2023). "In mammals, BRCA2 is highly expressed in the S-phase, and improper functions of the BRCA2 gene can result in replication errors in somatic cells that may later transform into cancer." (PMID 38213474, 2023). "In addition, multigene panel testing using NGS (next generation sequencing) technology could identify up to 50% more individuals with cancer susceptibility gene mutations in comparison with testing only for BRCA1 and BRCA2." (PMID 36707770, 2023). "Whilst accounting for a small proportion of cancer cases—0.1% of BC and around 1% of PCa—the risk for carriers to develop BC increases up to 1% and 7–8%, while for PCa it ranges to almost 4-fold increase and from 3 to 8.6-fold increase, for BRCA1 and BRCA2 mutations, respectively." (PMID 38203374, 2023). "Several structural variations are typical of BRCA1/2-deficient cancer genomes, including deletions up to 100 kb, unclustered tandem duplications of ∼10 kb associated with BRCA1 mutations, and deletions up to 1-10 kb in cancers are found in patients with BRCA2 mutations." (PMID 35783256, 2022). "Furthermore, we demonstrate that the combination of olaparib and TRAIL also kills cancer cells without BRCA2 mutations." (PMID 36358659, 2022). "BRCA1 was associated with mothers’ lifespan (HR = 1.64, P = 5.35 × 10−11); 139 of 190 BRCA2 PTVs and 73 of 98 BRCA1 PTVs identified in our study had previously been reported as pathogenic or likely pathogenic in Clinvar13 for heritable breast and ovarian cancer syndrome or related cancers." (PMID 37117740, 2022). "However, BRCA2 mutant tumors treated with PARP inhibitors have shown drug resistance caused by frame deletions of the BRCA2, which partially restore its DNA repair function, thereby allowing cancer cells to survive." (PMID 36613695, 2022). "Since, we found that all patients with BRCA2 mutant cancers in the COH cohort achieved pCR, and all our subsequent analyses also showed improved outcomes in BRCA2 mutant cancers, we grouped TNBCs harboring BRCA1 and BRCA2 pathogenic mutations together as BRCAmut cancers." (PMID 35857626, 2022). "Of patients who did not have a positive family history of any cancer (n = 487), 57 deleterious variants were detected in 54 patients, including BRCA2 (40.4%, 23/57), BRCA1 (22.8%, 13/57), PALB2 (10.5%, 6/57), NBN (5.3%, 3/57), MRE11A (5.3%, 3/57) and other genes (15.8%, 9/57)." (PMID 36232564, 2022).
cancer (continued). "Moreover, silencing of Brca2 in cancer cells is sufficient to induce Clu expression in CAFs of mouse tumors and in WT PSCs in culture, confirming not only that Clu is induced by BRCA deficiency but also that this is a non-cell-autonomous pathway induced by BRCA deficiency in the cancer cells." (PMID 36316305, 2022). "The history weighting algorithm call of benign for BRCA2 c.425G>T suggests that a variant allele producing as little as about 10% of functional transcript may not confer a high cancer risk." (PMID 33469799, 2022). "In addition, studies have found that patients with CHD4 deletion are sensitive to chemotherapy, but the deletion of CHD4 in BRCA2 mutant cells can enhance the resistance of cancer cells to cisplatin and PARP inhibitors by opening a channel known as “DNA damage tolerance”." (PMID 35548853, 2022). "Cancer onset is similar between BRCA2 carries and non-BRCA high-risk families." (PMID 35469032, 2022). "In addition, cancer risk genes other than BRCA1 and BRCA2 cannot be overlooked, which may contribute to HBOC susceptibility." (PMID 36230639, 2022). "Interestingly, the cells in the minor clone are all VIM positive with or without CK expression, likely to be circulating TME cells with clonal alterations while the presence of RB1 and BRCA2 losses in the minor clone indicated the probability of the generation of a new cancer clone." (PMID 35729213, 2022). "Moreover, given the differing cancer risk profiles between BRCA1 and BRCA2, it is unknown whether women’s reproductive decision-making differs between those harboring a BRCA1 vs. BRCA2 variant." (PMID 35326645, 2022). "Thus, the higher level of BRCA1 and BRCA2 mRNA observed in tumors may result from the proliferation status of cancer cells." (PMID 35203410, 2022). "Since the BRCA1 and BRCA2 proteins are also involved in the radiation-induced deoxyribonucleic acid (DNA) damage repair and signalling pathway, BRCA1+/− and BRCA2+/− carriers are considered to be at high risk of IR-induced cancer, notably through chest CT scan exams." (PMID 35301607, 2022). "However; despite being the earliest, most common and arguably most widely established paradigm of high penetrance cancer susceptibility, recent analyses suggest low ascertainment, with fewer than 3% of BRCA1/BRCA2 heterozygotes across Greater London identified." (PMID 35868849, 2022). "Also, patients with germline BRCA2 gene mutations and diagnosed with localized PCa had reduced cancer-specific survival compared to non-carriers." (PMID 34568039, 2021). "The pathogenetic role of mutations in BRCA1 and BRCA2, two key components of HR mechanism, has been largely established in several cancers such as breast, ovarian, prostate and PC, and BRCA1/2 germline mutations are among the most common causes of inherited cancer susceptibility." (PMID 34034685, 2021). "A set of variants characterized by an intermediate HR efficiency (hypomorphic variants) were also identified, which are still not classified in the case of BRCA2, but could correspond to a new class associated with an intermediate cancer risk." (PMID 34356684, 2021). "For example, for a variant in BRCA1/BRCA2, first, the patient with cancer may not be eligible for cancer treatments from which they would likely benefit, for example, platinum-based chemotherapy and/or poly ADP ribose polymerase (PARP) inhibitors." (PMID 33208383, 2021). "This was shown in lymphoid cells that are not known to be prone to BRCA2 related cancer risk." (PMID 35052422, 2021). "The same group estimated variants in one of 156 cancer predisposition genes among 2450 adult CCSs using whole-genome sequencing, with 11.8% of them carrying a pathogenic/likely pathogenic variant, and they frequently detected variants of Rb1, NF1, and BRCA2 genes." (PMID 34680213, 2021).
cancer (continued). "We then estimated how much the posterior probability is affected by whether or not clinical information such as pathologic profiles or personal/family cancer history exists, with specific focus on BRCA2, c.7522G>A, p.(Gly2508Ser) and BRCA1, c.5339T>C, p.(Leu1780Pro)." (PMID 34063308, 2021). "When including the discovery OC family, there was an increased carrier frequency of c.1813C>T in BRCA1 and BRCA2 pathogenic variant negative OC families versus sporadic OC cases (P = 0.01, Fisher’s exact) and cancer-free females (3/23, 13%; OR = 5.8; 95%CI = 1.7-19; P = 0.005)." (PMID 34861889, 2021). "Interestingly, the Hallmark DNA repair gene set does not include known DNA repair genes such as BRCA1 and BRCA2, arguably the most clinically relevant DNA repair genes associated with cancers." (PMID 33477315, 2021). "Interestingly, for patient BC03, an actionable BRCA2 mutation might also indicate PARP inhibitors as a potential treatment choice in the relapsed lesion, as the cancer cell fraction of this mutation was 94.3%." (PMID 33920370, 2021). "Thus, proper function of BRCA2 is crucial for cancer prevention, and miR-210-3p may target BRCA2 to impair its function and promote cancer progression." (PMID 33968986, 2021). "Heterozygous carriers of variants in a gene associated with autosomal recessive forms of FA are not at risk of FA, but may be at increased risk of breast, ovarian, and/or other cancers, if the monoallelic variants in question are in BRCA1, BRCA2, PALB2, BRIP1 or RAD51C." (PMID 34771713, 2021). "A large portion of inherited cancer risk caused by BRCA2 mutations may be accounted for by noncoding mutations." (PMID 33503928, 2021). "On average, the risk of cancer differs between the two genes, as for BRCA1 the assessed average risk of breast and ovarian cancers ranges from 57 to 65% and from 20 to 50%, respectively, and for BRCA2 the risk ranges from 35 to 57% and from 5 to 23%, respectively." (PMID 34026625, 2021). "Finally, among rare variants from the mother, as cancer driver genes, a missense mutant ALK (chr2: 30143039G > T, V163L, rs55697431), and a stop-gain mutant BRCA2 (chr13: 32911104C > A, S871Ter, rs397507634) were focused through screening using the IntOGen database." (PMID 34367235, 2021). "A patient’s prognosis for BRCA1/2-related cancer depends on the stage at which the cancer is diagnosed and on the type of mutation; however, studies of survival have revealed conflicting information for individuals with germline BRCA1 or BRCA2 pathogenic variants when compared to controls." (PMID 34207450, 2021). "It is therefore important to study and understand the hereditary mutations affecting the BRCA2 protein throughout the human population in order to increase the ability of clinicians to predict and treat cancers related to hypomorphic or nonfunctional BRCA2 alleles." (PMID 33503928, 2021). "Rare pathogenic variants in the BRCA1 and BRCA2 genes were selected as an exemplar for detailed analysis of clinically actionable variants in the UK Biobank, and BRCA related cancers (breast, ovarian, prostate, and pancreatic) were assessed in participants through use of cancer registry data." (PMID 33589468, 2021). "Indeed, a recent study has shown that BRCA1 and BRCA2 variants are rare (<0.2%) in the non-cancer FC population with no personal or family history of cancer relative to cancer cases." (PMID 34298626, 2021). "Interestingly, some cancers inappropriately express meiotic genes and recent evidence suggests that this may lead to altered BRCA2 function." (PMID 33996823, 2021). "Alternatively, it is possible that cells undergoing loss of heterozygosity in BRCA2 mutation carriers undergo apoptosis in the presence of RAD52 S346X variant, due to the persistence of unrepaired DSBs that may suppress tumorigenesis and reduce cancer risk." (PMID 32255263, 2020).